ZNF224 (zinc finger protein 224)
Description:
May be involved in transcriptional regulation as a transcriptional repressor. The DEPDC1A-ZNF224 complex may play a critical role in bladder carcinogenesis by repressing the transcription of the A20 gene, leading to transport of NF-KB protein into the nucleus, resulting in suppression of apoptosis of bladder cancer cells.
Synonyms: BMZF-2; BMZF2; KOX22; ZNF255; ZNF27
Tractability: PROTAC: UniProt records ubiquitination sites on it; ubiquitination databases record sites on it.
Gene: Protein-coding gene on chromosome 19 (44,094,326 to 44,109,886, forward strand). Ensembl gene ENSG00000267680.
Subcellular location: Nucleus
Subcellular location (Human Protein Atlas): Nuclear membrane; Nucleoplasm
Pathways (Reactome):
Gene expression (Transcription): Generic Transcription Pathway; Regulation of endogenous retroelements by KRAB-ZFP proteins
Gene Ontology:
Molecular function: DNA-binding transcription repressor activity, RNA polymerase II-specific; protein binding; sequence-specific DNA binding; transcription cis-regulatory region binding
Biological process: negative regulation of DNA-templated transcription; negative regulation of transcription by RNA polymerase II; regulation of transcription by RNA polymerase II; regulation of DNA-templated transcription
Cellular component: nuclear membrane; nucleoplasm; nucleus; transcription repressor complex
Genetic constraint (gnomAD): Loss-of-function variants: 8 observed, 10.3 expected, observed/expected ratio (o/e) 0.78, 90% interval 0.46 to 1.4. The upper end of that interval is the gene's LOEUF score, 1.4, which puts it in group 5 of 6, group 1 being the genes least tolerant of losing a copy. Missense variants: 708 observed, 838.07 expected, observed/expected ratio (o/e) 0.84, 90% interval 0.79 to 0.9. Synonymous variants: 274 observed, 280.29 expected, observed/expected ratio (o/e) 0.98, 90% interval 0.88 to 1.08.
Homologues: Orthologues: chimpanzee ZNF224 (99% identical), macaque ZNF224 (95% identical). Paralogues in human: ZNF225 (74% identical), ZNF221 (68% identical), ZNF284 (60% identical), ZNF227 (43% identical), ZNF235 (42% identical), ZNF229 (41% identical), ZNF226 (41% identical), ZNF234 (39% identical), ZNF33B (39% identical), ZNF28 (39% identical), ZNF726 (38% identical), ZNF728 (38% identical), and 164 more.
Diseases named in the same sentence as ZNF224 in open-access papers:
ZNF224 is named in the same sentence as 27 diseases in open-access papers, as found by Europe PMC text mining. Sharing a sentence is not in itself a finding about the gene and the disease. The quoted sentences say what the papers report.
bladder cancer (10 papers, 2012 to 2023). "ZNF224 showed higher expression in bladder cancer, liver cancer and breast cancer and acted as an oncogene by recruiting DEPDC1 to form a transcription complex." (PMID 36085146, 2022). "Among them, ZNF224 plays a crucial role in the NF-kB pathway activation in bladder cancer and myeloma cells, thus exerting an oncogenic function through the activation of anti-apoptotic and pro-survival signals." (PMID 36425656, 2022). "Previous reports showed that DEPDC1 interacts with ZNF224 to repress the transcription of A20, resulting in the activation of the NF-κB pathway in bladder cancer." (PMID 28969015, 2017). "It was identified as a molecular partner of ZNF224 in bladder cancer cells." (PMID 34684876, 2021). "DEPDC1 was firstly reported in bladder cancer with aberrantly high expression; it acted as a transcriptional repressor by forming a complex with zinc finger protein 224 (ZNF224) to suppress A20 transcription, leading to the activation of anti-apoptotic pathway through activating NF-κB pathway." (PMID 31032225, 2019). "Moreover, DEPDC1 repressed the transcription of A20 through interacting with ZNF224, leading to activate NF-κB pathway in bladder cancer." (PMID 31032225, 2019). "Previous reports have revealed that ZNF224 might play a critical role in bladder carcinogenesis by regulating the apoptosis of bladder cancer cells." (PMID 22574217, 2012). "To date, only one protein, ZNF224, has been identified to form a complex with DEPDC1 in bladder cancer cells." (PMID 28969015, 2017).
breast carcinoma (6 papers, 2016 to 2025). "This protein has been recently proposed as a new molecular partner of ZNF224 in breast cancer cells." (PMID 34684876, 2021). "ZNF224 also behaves as a transcriptional activator in different cellular contexts, such as breast cancer and CLL, where it induces cell growth and apoptosis resistance through the transcriptional activation of miR-663 and cyclin D genes, respectively." (PMID 34684876, 2021). "Among the tested KRAB-ZNFs, numerous studies demonstrate significant engagement of ZNF224 in the regulation of cancer development and progression, especially in melanoma, breast cancer, and Wilms tumor." (PMID 34638319, 2021). "ZNF224, besides its function as a transcriptional regulator in breast cancer and CLL, acts as a cofactor of the protein of Wilms tumor (WT1) and, in such a manner, can regulate WT1 apoptotic target genes in chronic myelogenous leukemia (CML) cells to exert a tumor‐suppressive role." (PMID 40321146, 2025). "Functionally, although no target genes of the ZNF224/MED28 complex have yet been identified, Cho and colleagues provided evidence that the interaction of ZNF224 and MED28 prevents ZNF224 degradation following DNA damage and consequently enhances the proliferation and survival of breast cancer cells." (PMID 34684876, 2021). "Finally, DEPDC1 and MED28 interact with ZNF224 in bladder and breast cancer cells, respectively, and elicit two different pathways involved in the promotion and progression of tumors in two distinctive cellular milieus." (PMID 34684876, 2021). "Furthermore, we assessed the expression of ZNF224 and miR-663a using human breast cancer tissues." (PMID 27105517, 2016). "In addition, ZNF224, by interacting with DEPDC1 and MED28 in bladder and breast cancer cells, respectively, stimulates two different pathways involved in the promotion and progression of tumors in these two cellular types." (PMID 40321146, 2025). "In bladder carcinogenesis, ZNF224, interacting with the transcriptional co-repressor DEPDC1, downregulates the expression of A20, a negative regulator of the NF-kB pathway, whereas, in breast cancer, ZNF224 acts as an oncogenic transcriptional activator." (PMID 34684876, 2021). "Indeed, it was recently demonstrated that ZNF224 increases miR-663a transcription, which in turn binds to 3′ UTR of p21 to decrease its expression in MCF-7 breast cancer cell line." (PMID 29423056, 2018).
chronic myelogenous leukemia (4 papers, 2015 to 2025). "The transcription factor ZNF224 plays a key proapoptotic role in chronic myelogenous leukemia (CML), by modulating Wilms Tumor protein 1 (WT1) dependent apoptotic genes transcription." (PMID 29423056, 2018). "We have previously shown that ZNF224 exerts a specific proapoptotic role in chronic myelogenous leukemia (CML) K562 cells and contributes to cytosine arabinoside-induced apoptosis, by modulating WT1-dependent transcription of apoptotic genes." (PMID 26320177, 2015). "Interestingly, ZNF224 expression was lower in chronic granulocytic leukemia and exhibited proapoptotic and antiproliferative effects with the ancillary transcription factor WT1." (PMID 36085146, 2022).
melanoma (4 papers, 2013 to 2025). A malignant, usually aggressive tumor composed of atypical, neoplastic melanocytes. "To evaluate the pro‐proliferative and anti‐apoptotic function of ZNF224 and, consequently, investigate the molecular mechanisms involved, we overexpressed or silenced ZNF224 in A375 and A2058 melanoma cell lines." (PMID 40321146, 2025). "Recently, we demonstrated that ZNF224 is a mediator of the pro‐oncogenic function of TGF‐β in melanoma, whose action is required to support tumor growth and progression, thus resulting in a strong reinforcement of cell migration and invasiveness." (PMID 40321146, 2025). "Reverse transcription quantitative PCR (RTqPCR) assays were performed on both melanoma cell lines, A375 and A2058, in which ZNF224 was overexpressed." (PMID 40321146, 2025). "In previous works, we identified ZNF224 as one of the mediators of the transforming growth factor beta (TGF‐β)‐induced pro‐tumoral activities in melanoma." (PMID 40321146, 2025). "The observation that ZNF224 overexpression enhanced p21 expression in melanoma cell lines prompted us to confirm a similar role in human melanoma biopsies." (PMID 40321146, 2025). "The tumorigenic molecular mechanism involving ZNF224, identified in this study, provides new insights into understanding melanoma development and progression, breaking ground in the research for new therapeutic tools." (PMID 40321146, 2025). "Analysis of expression levels correlation between ZNF224 and selected proliferation and survival key regulators in four human datasets from patients affected by melanoma." (PMID 40321146, 2025). "KRAB zinc finger protein ZNF224 acts as an oncogenic factor in melanoma cells, enhancing p21 cytosolic retention and impairing nuclear p21 cytostatic activity through stimulation of the AKT pathway." (PMID 40321146, 2025). "In this study, we strengthen our previous data on the pro‐oncogenic function of ZNF224 in melanoma by demonstrating the ZNF224 involvement in cell proliferation promotion and apoptosis inhibition as a regulator of the p21 function." (PMID 40321146, 2025). "We found that ZNF224 overexpression induced a dose‐dependent increase in Prom p21 transcriptional activity in the A375 melanoma cell line." (PMID 40321146, 2025). "Recently, in human melanoma cell lines, we demonstrated the involvement of ZNF224 in the TGF-β pathway, whose activation is a critical event in promoting tumor progression and invasion through the induction of the EMT process." (PMID 34684876, 2021). "To delve deeper into the molecular mechanisms by which ZNF224 could be involved in the proliferation and survival of melanoma cells, we checked at the protein level whether typical regulators of the cell growth and apoptosis were affected by ZNF224 modulation." (PMID 40321146, 2025). "Here, we identify an additional mechanism used by ZNF224 to affect melanoma progression." (PMID 40321146, 2025).
melanoma (continued). "Indeed, we demonstrated that sustaining the oncogenic function of the p21 protein is one of the ways by which ZNF224 promotes strong melanoma cell proliferation and inhibits cell death." (PMID 40321146, 2025). "Recently, we reported that ZNF224 expression supports the constitutive activation of the pro‐oncogenic pathway of TGF‐β in melanoma, through the upregulation of TGF‐β itself, its receptors, and various TGF‐β target genes involved in epithelial‐mesenchymal transition." (PMID 40321146, 2025). "Based on the results of this work, a new role for ZNF224 can be conceived in A375 melanoma cells." (PMID 40321146, 2025). "ZNF224 knockdown, on the contrary, increased the caspase 3/7 activity induced by cisplatin treatment, thus showing the protective function of ZNF224 against cisplatin‐induced apoptosis in melanoma cells." (PMID 40321146, 2025). "Finally, our recent findings highlighted the role of ZNF224 in melanoma cells through the enhancement of TGF-β pro-oncogenic function." (PMID 34684876, 2021). "To investigate whether the immunophilin interacted with DNA, we performed chromatin immunoprecipitation assays (ChIP) using anti-Flag antibody in melanoma cells transfected with FKBP51-Flag or the zinc-finger protein ZNF224-Flag37 as positive control." (PMID 23559012, 2013). "Indeed, our experiments demonstrated that ZNF224 may act as a regulatory component of the AKT/p21 pathway in A375 melanoma cells, being involved in the activation of AKT and p21 phosphorylation." (PMID 40321146, 2025). "However, considering its role in the regulation of multiple proliferative and anti‐apoptotic signaling pathways, therapeutic strategies based on the down‐modulation of ZNF224 could constitute an attractive adjuvant in the treatment of melanoma." (PMID 40321146, 2025). "Finally, we evaluated whether the ability of ZNF224 to induce cell proliferation in melanoma cell lines was dependent, at least in part, on its role in the activation of AKT." (PMID 40321146, 2025). "As well as in A375, AKT inhibition reduced the proliferative function of ZNF224, thus suggesting that activated AKT is crucial for ZNF224‐mediated proliferation modulation in both melanoma cell lines." (PMID 40321146, 2025). "ZNF224 stimulates the expression of TGF-β- regulated genes that are involved in epithelial–mesenchymal transition (EMT) and thus it promotes the proliferation and invasiveness of melanoma cells." (PMID 34684876, 2021). "Finally, we found that ZNF224 overexpression promotes p21 oncogenic cytoplasmic localization through the activation of the AKT pathway, thus contributing to enhanced proliferation and survival of melanoma cells." (PMID 40321146, 2025).
chronic lymphocytic leukemia (3 papers, 2021 to 2022). "In chronic lymphocytic leukemia (CLL), ZNF224 acts as a direct transcriptional activator of the cyclin D3 gene, thus exerting an important role in cell growth and drug resistance." (PMID 34684876, 2021). "Oncogenic features of ZNF224 have also been documented in BRCA and chronic lymphocytic leukemia (CLL), specifically in terms of increased chemoresistance against camptothecin and fludarabine, respectively." (PMID 33672287, 2021).
Alzheimer disease (2 papers, 2012 to 2017). A progressive, neurodegenerative disease characterized by loss of function and death of nerve cells in several areas of the brain leading to loss of cognitive function such as memory and language. "(2010) observed associations of ZNF224 (rs3746319) and PCK1 (rs8192708) with impaired cognition, an intermediate phenotype of Alzheimer's disease." (PMID 29201552, 2017). "That same year, researchers used neuropathology and cognitive function proximate to death as the intermediate phenotypes for Alzheimer disease and identified two genes—ZNF224 and PCK1—involved in the development of Alzheimer disease." (PMID 23094028, 2012).
leukemia (2 papers, 2015 to 2021). A malignant (clonal) hematologic disorder, involving hematopoietic stem cells and characterized by the presence of primitive or atypical myeloid or lymphoid cells in the bone marrow and the blood. "Additional studies indicated that cytosine arabinoside (ara-C or cytarabine) chemotherapeutic used in leukemias augmented the expression of ZNF224, which was accompanied by enhanced apoptosis." (PMID 33672287, 2021). "We also demonstrated that ZNF224 plays a relevant role in ara-C-induced apoptosis of leukemia cells." (PMID 26320177, 2015). "Another set of publications from the Constanzo/Cesaro group points towards ZNF224 TSG function, particularly in the context of increased sensitivity to drug treatment in human leukemias." (PMID 33672287, 2021). "In addition, our molecular data are suggestive of a regulatory loop in which WT1, by repressing the expression of ZNF224 gene, could prevent the proapoptotic effect of the ZNF224-WT1 complex itself, thus contributing to the WT1 pro-survival role in leukemia." (PMID 26320177, 2015).
Wilms tumor (2 papers, 2021). An embryonal neoplasm characterized by the presence of epithelial, mesenchymal, and blastema components. "WT1 is the protein of Wilms tumor, a sporadic childhood kidney cancer that is genetically heterogeneous, which was the first identified interacting protein of ZNF224 and ZNF255." (PMID 34684876, 2021).
Brain atrophy (1 paper, 2010). Partial or complete wasting (loss) of brain tissue that was once present. "For the primary analysis, we used an additive model to assess whether the following late onset AD-associated variants influence brain atrophy and cognitive dysfunction in MS patients: PICALM (rs3851179), CR1 (rs6656401), CLU (rs11136000), PCK1 (rs8192708), and ZNF224 (rs3746319)." (PMID 21152065, 2010).
breast ductal carcinoma (1 paper, 2016). "The analyses using human breast ductal carcinoma tissues exhibited that the expression of ZNF224 and miR-663a was increased in cancer compared to non-cancer region." (PMID 27105517, 2016).
cognitive decline (1 paper, 2010). "Finally, in a series of statistical mediation analyses, we tested hypotheses about the causal chain of events linking genetic variation in the ZNF224 and PCK1 loci with cognitive decline, with strikingly different outcomes." (PMID 20574532, 2010).
Cognitive impairment (1 paper, 2010). Abnormal cognition is characterized by deficits in thinking, reasoning, or remembering. "The association of ZNF224 with cognitive impairment was mediated by neurofibrillary tangles, whereas PCK1 largely influenced cognition independent of AD pathology, as well as Lewy bodies and infarcts." (PMID 20574532, 2010). "In the case of ZNF224, we find that AD pathology, and more specifically, neurofibrillary tangles mediate an association with cognitive impairment." (PMID 20574532, 2010). "Episodic memory impairment, the most characteristic cognitive deficit of AD, was associated with both the ZNF224 locus (p = 0.003) and the PCK1 locus (p = 3.69×10−4)." (PMID 20574532, 2010).
colorectal cancer (1 paper, 2025). A primary or metastatic malignant neoplasm that affects the colon or rectum.